TSLP (thymic stromal lymphopoietin)
Diseases named in the same sentence as TSLP in open-access papers (continued):
Sharing a sentence is not in itself a finding about the gene and the disease.
asthma (continued). "It should be underlined that in our three study groups, only patients with asthma were characterized by a very strong positive correlation between IS periostin and TSLP concentrations both at the protein and mRNA levels (r = 0.96 and r = 0.95, respectively)." (PMID 33203095, 2020). "The aim of the study was to evaluate the impact of interactions between DCs and nasal epithelial cells co-cultured with macrophages on the expression of TSLP, IL-33, and IL-17A in asthma, COPD, and controls." (PMID 32842623, 2020). "In patients with asthma, both IS concentration and mRNA expression of periostin and TSLP correlated positively with IS eosinophil count." (PMID 33203095, 2020). "TSLP, one of key cytokines, lies at the start of the inflammatory cascade in asthma, functioning as an upstream “master switch” in the epithelium." (PMID 32120846, 2020). "High sputum TSLP levels may be induced by overexpressed periostin in the airway epithelium, but the specific mechanisms underlying the concurrent increase in local TSLP and periostin levels in asthma need further investigation in in vitro and in vivo experimental studies." (PMID 33203095, 2020). "A strong positive correlation between IS periostin and TSLP protein levels (r = 0.95, p < 0.001) as well as mRNA expression level (r = 0.95, p < 0.001) was found in patients with asthma." (PMID 33203095, 2020). "In clinical settings, tezepelumab, a human monoclonal antibody specific for TSLP, reduced the rate of asthma exacerbation in patients with uncontrolled asthma." (PMID 32397396, 2020). "Epithelial-derived cytokines such as thymic stromal lymphopoietin (TSLP), IL-25 and IL-33 are important factors in the pathogenesis of asthma as they promote Th2-associated immune responses via activation of DCs." (PMID 32477356, 2020). "Background and objectives: Cytokine thymic stromal lymphopoietin (TSLP) plays a pivotal role in the pathogenesis of atopic diseases such as atopic dermatitis, allergic rhinitis, and asthma." (PMID 33379407, 2020). "Tezepelumab, an anti‐TSLP human monoclonal antibody, has shown efficacy in inhibiting both early and late asthma responses, as well as blood eosinophilia and clinical parameters." (PMID 32714552, 2020). "One such potential target is thymic stromal lymphopoietin (TSLP), an epithelial-derived cytokine released in response to multiple triggers associated with asthma exacerbations, such as viruses, allergens, pollutants and other airborne irritants." (PMID 33059715, 2020). "Co-cultivation of moDCs with epithelial cells and moMφs increased TSLP mRNA expression with the most pronounced effect observed in asthma." (PMID 32842623, 2020). "Such a correlation was also observed for TSLP in patients with either asthma or COPD (r = 0.95 and r = 0.64, respectively, p < 0.001 for both), but not in controls." (PMID 33203095, 2020). "We replicated previous GWAS results, reporting a significant association of TSLP and RORA gene variants with asthma and GCKR, PNPLA3, TRIB1 and TM6SF2 gene variants with the risk of developing liver diseases, notably NAFLD/NASH." (PMID 30978214, 2019). "As a consequence, TSLP targeting by means of tezepelumab (anti-TSLP antibody) is in clinical trials for asthma and atopic dermatitis." (PMID 31387206, 2019). "IL-25 and TSLP are epithelial-derived cytokines that play an essential role in stimulating Th2 cytokine response and initiating airway type 2 inflammation in asthma." (PMID 31885750, 2019). "Bronchial epithelial cell injury leads to production of type 2 alarmins such as IL-33 and TSLP, also in asthma." (PMID 30778348, 2019). "TSLP has pleiotropic biological and pathological functions;with overexpression of TSLP detected in several allergic diseases, including asthma, AD, AR and food allergy." (PMID 31768185, 2019).
asthma (continued). "The human anti-TSLP antibody tezepelumab has decreased the annualized rate of asthma attacks in patients with uncontrolled asthma who were already being treated with medium to high doses of inhaled glucocorticoids and long-acting β-agonists." (PMID 31284537, 2019). "The anti-TSLP antibody also exerts preventive effects on airway structural changes for smooth muscle thickness in asthma." (PMID 31284537, 2019). "Among asthmatic patients, OX40L level positively correlated with airway inflammation, such as serum IgE, percentages of eosinophils and neutrophils, serum IL-6 and TSLP, and negatively correlated with asthma severity (ACT score) and pulmonary function (FEV1%)." (PMID 30890137, 2019). "Thymic stromal lymphopoietin (TSLP) is an important cytokine that enhances allergic reactions and is highly expressed in bronchial epithelial cells in asthma patients." (PMID 31167385, 2019). "The release of the major stimulators of ILC2s, TSLP, IL-25, and IL-33, as a result of epithelial cell injury in both asthma and COPD, provide evidence of ILC2s in airway remodeling." (PMID 31354734, 2019). "To date, a new clinical trial evaluating the effects of anti-TSLP in adult patients with asthma (UPSTREAM) is ongoing." (PMID 31355170, 2019). "The importance of TSLP in asthma is highlighted by clinical studies using a monoclonal anti-TSLP antibody." (PMID 31191511, 2019). "Another relevant cytokine reported upon hRSV infection is the thymic stromal lymphopoietin (TSLP), a cytokine associated with asthma development." (PMID 30936869, 2019). "In an asthma model, TSLP can upregulate natural killer T cells to increase IL-13 production and decrease airway hyperreactivity." (PMID 31284537, 2019). "Group 1 consists of an anti-TSLP antibody, anti-IL-33R antibody, anti-IL-33R antibody, anti-IL-25 antibody, and anti-IL-6 antibody, which are investigational drugs for asthma." (PMID 31284537, 2019). "Corticosteroids are a common treatment for asthma, but TSLP can enhance the survival and proliferation of IL-13+ ILC2s through STAT5 activation, thus limiting therapeutic effectiveness." (PMID 31921158, 2019). "Salmeterol is a long-acting β2 agonist drug that reduces the severity of asthma in children by suppressing TSLP secretion in human bronchial ECs." (PMID 31284537, 2019). "TSLP targeting with an anti-TSLP human monoclonal antibody has been utilized in the treatment of uncontrolled asthma with clinical improvements and is currently under investigation in several studies to evaluate efficacy and safety." (PMID 30760333, 2019). "Both anti-TSLP and anti–IL-33 therapies were clinically proven to reduce asthma exacerbations and allergic dermatitis symptoms, respectively, and are moving forward in clinical development." (PMID 31184997, 2019). "We (Semlali, Jacques, Koussih, Gounni, & Chakir, 2010) and other authors have previously demonstrated that TSLP expression is upregulated in asthma patients relative to healthy controls." (PMID 31290290, 2019). "Mast cells are normally located just beneath epithelial cells, and in asthma, they are also found within the intraepithelial cell layer, and they are therefore capable of rapidly responding to TSLP and IL-33 released from epithelial cells." (PMID 31275312, 2019). "Two asthma-associated SNPs (rs11071559 (RORA) and rs1837253 (TSLP)) passed the significance threshold of <0.05 and were directionally consistent with previous studies." (PMID 30978214, 2019). "Salmeterol is a long-acting β2-agonist drug that reduces the severity of asthma in children and suppresses TSLP secretion in human bronchial epithelial cells." (PMID 29670037, 2018). "TSLP is highly expressed in human cutaneous epithelial cells in AD and bronchial epithelial cells in asthma and is believed to participate in the progression from severe AD to asthma and allergic rhinitis (“atopic march”)." (PMID 29320511, 2018).
asthma (continued). "Expression levels of TSLP, the master-regulator of airway remodeling during asthma, and of TGFβ1, which is involved in airway inflammation and hyper-responsiveness, were also decreased in IL-6 KO mice as compared to WT mice." (PMID 30534125, 2018). "Aberrant levels of TSLP have been observed in a variety of airway diseases, such as asthma, chronic obstructive pulmonary disease, and nasal polyps." (PMID 30013577, 2018). "TSLP, IL-33, and IL-25 are key mediators of type-2 inflammation diseases (such as asthma, nasal polyposis, and Eosinophilic esophagitis); therefore they are deserving an increasing interest as potential target of new drugs." (PMID 29992143, 2018). "Mice overexpressing TSLP in the airway epithelium develop an inflammatory disease with characteristics of asthma." (PMID 30057581, 2018). "The human anti-TSLP antibody named tezepelumab in the phase 2 study had a reduced annualized rate of asthma attack on uncontrolled asthmatic adults that were already treated with medium-to-high doses of inhaled glucocorticoids and long-acting β-agonists." (PMID 29670037, 2018). "In a mouse model of asthma microRNA-19b (miR-19b) reduces airway inflammation and remodeling by inhibiting Stat3 signaling through TSLP downregulation." (PMID 30057581, 2018). "Among them, periostin and TSLP are well-characterized T-helper 2 type markers with specific roles in various stages of asthma pathogenesis." (PMID 29580282, 2018). "TSLP also upregulates interleukin-13 (IL-13) production in natural killer T cells and decreases airway hyper-reactivity in an asthma model." (PMID 29670037, 2018). "Thymic stromal lymphopoietin (TSLP) is an important factor responsible for the pathogenesis of allergic diseases, such as atopic dermatitis and asthma." (PMID 30011850, 2018). "The anti-TSLP antibody reduces allergen-induced bronchoconstriction in patients with allergen-induced asthma." (PMID 29670037, 2018). "Release of epithelial cytokines, IL-33, IL-25, and TSLP, is the initial process during asthma exacerbation." (PMID 29977243, 2018). "Recent evidence suggests that elevated expression of TSLP in the airways is a biomarker of severe refractory asthma." (PMID 30057581, 2018). "Thymic stromal lymphopoietin (TSLP) is an epithelial and mast cell-derived cytokine linked to allergic diseases such as asthma and atopic dermatitis (AD)." (PMID 29320511, 2018). "Studies in mouse models of asthma have clearly demonstrated that TSLP is a key initiator of allergic airway inflammation." (PMID 29343779, 2018). "Studies have reported that TSLP played important roles in inflammatory diseases, including asthma and Behçet’s disease." (PMID 30123216, 2018). "In fact, TSLP appears to be a key cytokine for the progression of the atopic march (atopic dermatitis to asthma), and treatment with anti-TSLP compounds is expected to have important clinical effects." (PMID 29862299, 2018). "There is an increased expression of TSLP messenger RNA and proteins in the airways of asthmatic patients compared to controls, and the degree of expression correlated with severity of asthma and lung function." (PMID 30386455, 2018). "Considered as a master switch in T helper 2 lymphocyte (Th2) mediated responses, TSLP is believed to play a key role in allergic diseases including asthma." (PMID 29320511, 2018). "Ex vivo RSV infection of human airway epithelial cells of healthy children and children with asthma results in TSLP induction and has been shown to contribute to Th2 inflammation." (PMID 29915592, 2018). "Genes such as HLA, IL13, IL33, thymic stromal lymphopoietin (TSLP) involved in Th2 pathway, IL-1 receptor–like 1 (IL1RL1), encodes ST2, and the receptor for IL-33 are associated with asthma onset." (PMID 29904594, 2018).
asthma (continued). "Using inhibitors, it was preciously shown that serine proteases activity from Alternaria induced TSLP and IL-33, potentially playing an important role in the development of allergic inflammation, airway disease, and severe asthma exacerbations." (PMID 30100902, 2018). "Thymic stromal lymphopoietin (TSLP) is an important factor responsible for the pathogenesis of allergic diseases, such as AD and asthma." (PMID 30011850, 2018). "Ever since TSLP was first implicated as a driver of Th2 responses in the airways, aberrant levels of TSLP have been observed in a range of airway diseases, such as asthma, COPD, and nasal polyps." (PMID 28202030, 2017). "TSLP has a high expression in patients with asthma, allergic rhinitis, and atopic dermatitis, which is associated with the relative signal pathway in the pathogenesis of these diseases." (PMID 28085100, 2017). "Lastly, the pro-inflammatory cytokine, thymic stromal lymphopoietin (TSLP) is highly expressed in ASM bundles from asthma and COPD patients, and human ASMCs express its receptor TSLPR." (PMID 28814293, 2017). "There was a strong expression of TSLP, IL-25, and IL-33 in the epithelium, the endothelium of small vessels and subepithelial infiltrating cells in the nasal tissue derived from severe asthma patients with CRS (respectively)." (PMID 28199345, 2017). "The pro-inflammatory cytokine thymic stromal lymphopoietin (TSLP) is pivotal to the pathophysiology of widespread allergic diseases mediated by type 2 helper T cell (Th2) responses, including asthma and atopic dermatitis." (PMID 28368013, 2017). "Among susceptibility factors for asthma, the genes IL1RL1/IL18R1, IL33, and TSLP have emerged as some of the most important associated with development of the disease, linking epithelium-derived cytokines to type 2 inflammation." (PMID 28583446, 2017). "Applying this analysis to bronchial epithelial cells has revealed SNPs in TSLP, GSDMB, IL33, HLA-DQB1, C11orf30, DEXI, CDHR3, and ZBTB10 that affect asthma risk by allowing cis-regulation of its gene expression in an epithelial specific manner." (PMID 28583446, 2017). "Thymic stromal lymphopoietin (TSLP) is an epithelial-derived cytokine and has a relationship with Th2 response in asthma." (PMID 28815006, 2017). "Higher expression of Th2-driven cytokines (IL-4, IL-5, IL-9, and IL-13), TSLP, IL-25 and IL-33 in nasal tissues was observed in severe asthma." (PMID 28199345, 2017). "The emergence of human TSLP as a clinical target against asthma calls for maximally harnessing its therapeutic potential via structural and mechanistic considerations." (PMID 28368013, 2017). "Epithelial cell-derived cytokines, including thymic stromal lymphopoietin (TSLP), IL-25, and IL-33 are critical regulators of innate and adaptive immune responses associated with Th2 cytokine-mediated inflammation in asthma." (PMID 28199345, 2017). "Currently in phase II clinical trials, it has been shown to be a useful tool for the management of moderate-to-severe asthma, highlighting the relevance of TSLP signaling as a therapeutic target." (PMID 29222519, 2017). "In fact, Phase II trials are currently proceeding using an anti-TSLP antibody; AMG 157 from Amgen Corp., to neutralise the TSLP cytokine for the treatment of allergic diseases as asthma." (PMID 27658857, 2016). "We found that the serum levels of IL-5, IL-13 and TSLP were significantly elevated in patients with asthma compared with controls." (PMID 26956917, 2016). "In this study, we concentrated on the possible association between TSLP and the hypersensitive reaction in a DEHP oral exposure mouse asthma model, and tried to discover the mechanisms relating to these DEHP immunoadjuvant effects." (PMID 27467143, 2016). "A monoclonal antibody targeting and inhibiting TSLP is currently in clinical phase III trials for asthma and allergic inflammation after a promising phase II trial." (PMID 27149122, 2016).
asthma (continued). "Serum IL-31 levels correlated positively with Th2 related cytokines (IL-5, IL-13, and TSLP), asthma severity or total serum immunoglobulin E (IgE), and inversely with asthma control and the forced expiratory volume in 1 second (FEV1)." (PMID 26956917, 2016). "In this study, a chronic OVA-induced mouse model of asthma was used to investigate the role of TSLP in the DEHP-adjuvant effect on the coallergen (OVA)." (PMID 27467143, 2016). "Three bronchial epithelial upstream cytokines; IL-33, TSLP and IL-25 are considered to trigger type-2 inflammation in asthma." (PMID 26879906, 2016). "In a murine model of asthma, blockade of TSLP signaling reduced airway inflammation by down-regulating murine DC function." (PMID 26992000, 2016). "TSLP in the context of allergy has so far been more extensively studied in atopic dermatitis and asthma." (PMID 26793299, 2015). "Recently, a preliminary trial in patients with allergen-induced asthma and airway inflammation has found a therapeutic value for an anti-TSLP monoclonal immunoglobulin." (PMID 26793299, 2015). "Most recently, thymic stromal lymphopoietin (TSLP) has been shown to contribute to the pathogenesis of asthma and treatment of asthmatic patients with a monoclonal antibody directed against TSLP improves respiratory function." (PMID 25642424, 2015). "IL-25, IL-33 and/or TSLP were increased in specimens from patients with asthma and in inflamed skin lesions of patients with atopic dermatitis." (PMID 26230091, 2015). "As a key driver of Th2 immune responses, TSLP has been postulated to play a major pathogenetic role in asthma." (PMID 25775429, 2015). "Thymic stromal lymphoproetin (TSLP) is a cytokine secreted by the airway epithelium in response to respiratory viruses and it is known to promote allergic Th2 responses in asthma." (PMID 25546419, 2014). "Collectively, these results suggest that virally-induced TSLP apical secretion modulate the immune secretory phenotype in asthma, characterized by the production of Th2-related chemokines in the bronchial epithelium during acute exacerbations." (PMID 25546419, 2014). "TSLP is an epithelial-derived cytokine that contributes to the generation of allergic airway inflammation in asthma." (PMID 25546419, 2014). "It has been shown that epithelial cell damage caused by a number of chemicals or viral exposure significantly contributed to the increased allergic responses and asthma pathogenesis through the expression of alarmins such as IL-33 and TSLP." (PMID 25202911, 2014). "We observed that TSLP is a pivotal contributor to airway remodeling in mice with chronic allergen-induced asthma." (PMID 23300949, 2013). "ILC2 are activated both by epithelial-derived cytokines such as IL-25, IL-33, and TSLP as well as leukotrienes found elevated in asthma, and yet ILC2 also produce amphiregulin, an important tissue repair mediator." (PMID 24876829, 2013). "TSLP can induce multiple signaling pathways in asthma, including STAT6, IL-4, IL-1β and TNFα, p38 and Jun kinase (JNK )." (PMID 24167583, 2013). "Subsequent studies have shown increased levels of IL-25, IL-33, and TSLP in patients with asthma that all have the potential to active ILC2." (PMID 24876829, 2013). "Here we further demonstrate that cellular senescence is required in TSLP-induced of airway remodeling in asthma." (PMID 24167583, 2013). "Genome-wide association (GWA) studies on asthma have suggested that several polymorphisms in several genes, including ORMDL3-GSDMB, DENND1B, HLA-DP, SLC30A8, IL1RL1-IL18R1, IL33, SMAD3, TSLP, and NOTCH4 are associated with asthma." (PMID 23861779, 2013). "Previous reports have demonstrated the central role of Stat3 signaling in TSLP-regulated inflammation and airway remodeling in asthma." (PMID 24167583, 2013). "The aim of the present study was to investigate the effect of TSLP neutralization with an anti-TSLP mAb on the airway structural alterations in a murine model of chronic HDM exposure-induced asthma." (PMID 23300949, 2013).